PRSS54 (serine protease 54)
Synonyms: CT67; KLKBL4; FLJ25339
Tractability: Antibody: UniProt places it where antibodies can reach, with high confidence; UniProt predicts a signal peptide or a membrane-spanning region; its Gene Ontology location is reachable by antibodies, with medium confidence.
Gene: Protein-coding gene on chromosome 16 (58,279,997 to 58,295,047, reverse strand). Ensembl gene ENSG00000103023.
Subcellular location: Secreted
Gene Ontology:
Molecular function: serine-type endopeptidase activity
Biological process: proteolysis
Cellular component: extracellular region
Genetic constraint (gnomAD): Loss-of-function variants: 17 observed, 22.48 expected, observed/expected ratio (o/e) 0.76, 90% interval 0.52 to 1.13. The upper end of that interval is the gene's LOEUF score, 1.13, which puts it in group 4 of 6, group 1 being the genes least tolerant of losing a copy. Missense variants: 444 observed, 521.16 expected, observed/expected ratio (o/e) 0.85, 90% interval 0.79 to 0.92. Synonymous variants: 177 observed, 206.26 expected, observed/expected ratio (o/e) 0.86, 90% interval 0.76 to 0.97.
Homologues: Orthologues: chimpanzee PRSS54 (99% identical), macaque PRSS54 (92% identical), pig PRSS54 (65% identical), dog PRSS54 (63% identical), guinea pig PRSS54 (61% identical), mouse Prss54 (58% identical), rabbit PRSS54 (58% identical), rat Prss54 (55% identical), Drosophila melanogaster CG4477 (15% identical), Drosophila melanogaster Send2 (13% identical), Drosophila melanogaster CG31269 (12% identical), Drosophila melanogaster CG12256 (12% identical), and 7 more. Paralogues in human: TMPRSS4 (17% identical), KLK7 (14% identical), KLK8 (13% identical), KLK12 (13% identical), KLK2 (13% identical), KLK5 (13% identical), KLK1 (13% identical), KLK3 (13% identical), KLK11 (13% identical), KLK14 (13% identical), KLK4 (12% identical), PRSS58 (12% identical).
Diseases named in the same sentence as PRSS54 in open-access papers:
PRSS54 is named in the same sentence as 8 diseases in open-access papers, as found by Europe PMC text mining. Sharing a sentence is not in itself a finding about the gene and the disease. The quoted sentences say what the papers report.
breast cancer (1 paper, 2025). A primary or metastatic malignant neoplasm involving the breast. "This study hypothesized that epigenetic processes, including DNA methylation, influence the expression of identified CG or testis-specific genes, such as SYCP1, ADAD1, SYCE1, PRSS54, DMRTC2, and TEX101, in breast cancer (BC), normal breast (NB), and chronic myelogenous leukemia (CML) cell lines." (PMID 41411337, 2025).
leukemia (1 paper, 2025). A malignant (clonal) hematologic disorder, involving hematopoietic stem cells and characterized by the presence of primitive or atypical myeloid or lymphoid cells in the bone marrow and the blood. "Differential methylation analysis revealed cancer-specific patterns: ADAD1 was hypermethylated in both malignancies, while PRSS54 was hypomethylated in leukemia." (PMID 41411337, 2025). "For leukemia patients, SYCE1 again displays relatively prolonged survival, while PRSS54 and TEX101 are linked to a more rapid decline." (PMID 41411337, 2025). "This suggests tissue-specific epigenetic regulation, where PRSS54 may act as an oncogene in leukemia but a tumor suppressor in BC." (PMID 41411337, 2025). "In leukemia versus healthy donors, GO enrichment revealed that TEX101, ADAD1, PRSS54, and SYCE1 were the most enriched genes, whereas SYCP1 and DMRTC2 exhibited minimal enrichment." (PMID 41411337, 2025). "We comprehensively analyzed differential methylation, survival analysis (Kaplan-Meier), correlation (Spearman’s), and pathway enrichment analysis (GO/KEGG) of CG genes (SYCP1, ADAD1, SYCE1, PRSS54, DMRTC2, and TEX101) in BC and leukemia." (PMID 41411337, 2025). "Leukemia showed an inverse trend, with SYCP1 and ADAD1 hypermethylated, while PRSS54 was strikingly hypomethylated (~0.08 vs. ~ 0.86 normal)." (PMID 41411337, 2025). "In leukemia versus healthy blood donors, SYCP1, ADAD1, and SYCE1 were hypermethylated (~0.35 vs. ~ 0.17, ~ 0.84 vs. ~ 0.44, and ~0.45 vs. ~ 0.09, respectively), while PRSS54 was markedly hypomethylated (~0.08 vs. ~ 0.86)." (PMID 41411337, 2025).
tumor (2 papers, 2021 to 2025). "In contrast, SYCE1 and PRSS54 displayed reduced methylation in BC tumor (~0.26 vs. ~ 0.52 and ~0.20 vs. ~ 0.37, respectively)." (PMID 41411337, 2025). "For tumor stage, SYCP1 and ADAD1 showed negligible positive correlations (ρ = 0.02, 0.08, respectively), while SYCE1, PRSS54 and DMRTC2 exhibited slight negative correlations." (PMID 41411337, 2025).
cancer (1 paper, 2025). A tumor composed of atypical neoplastic, often pleomorphic cells that invade other tissues. "SYCP1 and SYCE1 maintained modest inverse correlations, whereas PRSS54 and TEX101 showed no significant methylation-expression relationship, highlighting the cancer-specific nature of these epigenetic interactions." (PMID 41411337, 2025).
PRSS54 also shares sentences with these, for which no sentence is quoted: colon cancer (1 paper); invasive breast carcinoma (1); prostate adenocarcinoma (1); sarcoma (1).